SNURF (SNRPN upstream open reading frame)
Tractability: PROTAC: ubiquitination databases record sites on it.
Gene: Protein-coding gene on chromosome 15 (24,954,987 to 24,977,850, forward strand). Ensembl gene ENSG00000273173.
Subcellular location: Nucleus
Subcellular location (Human Protein Atlas): Nuclear speckles
Gene Ontology:
Molecular function: ATPase binding
Cellular component: nuclear speck; nucleus
Genetic constraint (gnomAD): Loss-of-function variants: 6 observed, 12.23 expected, observed/expected ratio (o/e) 0.49, 90% interval 0.27 to 0.97. The upper end of that interval is the gene's LOEUF score, 0.97, which puts it in group 4 of 6, group 1 being the genes least tolerant of losing a copy. Missense variants: 84 observed, 92.07 expected, observed/expected ratio (o/e) 0.91, 90% interval 0.76 to 1.09. Synonymous variants: 29 observed, 33.58 expected, observed/expected ratio (o/e) 0.86, 90% interval 0.64 to 1.18.
Homologues: Orthologues: chimpanzee SNURF (97% identical), guinea pig SNURF (96% identical), mouse Snurf (96% identical), pig SNURF (96% identical), macaque SNURF (94% identical), rat Snurf (93% identical), rat Snurf-ps2 (80% identical).
Diseases named in the same sentence as SNURF in open-access papers:
SNURF is named in the same sentence as 10 diseases in open-access papers, as found by Europe PMC text mining. Sharing a sentence is not in itself a finding about the gene and the disease. The quoted sentences say what the papers report.
Angelman syndrome (2 papers, 2022 to 2025). A neurogenetic disorder characterized by severe intellectual deficit and distinct facial dysmorphic features. "Moreover, a cluster of genes in the BTA21 (GABRG3, MAGEL2, MKRN3, NDN, SNRPN, and SNURF) was significantly associated (FDR = 1.07 × 10−6) with the Prader-Willi and Angelman syndromes pathway in the PPI analysis." (PMID 35692843, 2022).
acute myeloid leukemia (1 paper, 2022). Acute myeloid leukemia (AML) is a group of neoplasms arising from precursor cells committed to the myeloid cell-line differentiation. "Warner et al13 compared the expression levels of snoRNA in 33 cases of acute myeloid leukemia (AML) and 6 normal blood samples, and found that a series of snoRNA molecules were abnormally expressed in AML patients, of which 37 snoRNAs were located in the DLK1-DIO3 or SNURF-SNRPN imprinted regions." (PMID 36518603, 2022).
cognitive deficits (1 paper, 2021). "Mice with a targeted deletion of SNORD116 show cognitive deficits, abnormal growth and feeding, while mice with paternal deletions of portions of SNURF or SNRPN seem to have a normal phenotype." (PMID 34200226, 2021).
COVID-19 (1 paper, 2024). A disease caused by infection with severe acute respiratory syndrome coronavirus 2. "In addition, SNURF is expressed in several other tissues, including the brain, corroborating the association of anti-SNURF IgG and neuropsychiatric symptoms post-COVID-19." (PMID 39414823, 2024).
Prader-Willi syndrome (1 paper, 2020). "Deletion of genes from this region inherited from the father (MKRN3, MAGEL2, NDN, SNURF-SNPRN genes) leads to Prader-Willi syndrome (PWS)." (PMID 33375093, 2020).
SNURF also shares sentences with these, for which no sentence is quoted: breast tumor (1 paper); cancer (1); Hematological Disease (1); lung carcinoma (1); Obesity (1).